CHD5 (chromodomain helicase DNA binding protein 5)
Diseases named in the same sentence as CHD5 in open-access papers (continued):
Sharing a sentence is not in itself a finding about the gene and the disease.
colorectal cancer (7 papers, 2012 to 2017). A primary or metastatic malignant neoplasm that affects the colon or rectum. "The ARID1A, BCR, CHD5, RPL22 and TSC2 genes were shared mutation targets in ovarian and colorectal carcinomas." (PMID 29296220, 2017). "The low expression of CHD5 in colorectal cancer is correlated with hypermethylation of the CpG island in the CHD5 promoter and translational repression mediated by miR-211." (PMID 24454811, 2014). "First, we examined the expression levels of miR-211 and CHD5 in the colorectal cancer cell lines RKO and HCT-116." (PMID 22235338, 2012). "In the present study, we investigated the role of miR-211 on colorectal cancer cells through its downregulation of CHD5 in vitro and in vivo." (PMID 22235338, 2012). "In the present study, we determined that enforced expression of miR-211 in a colorectal cancer cell line directly downregulates CHD5, resulting in increased cell viability, cell cycle progression, and migration ability and decreased apoptosis." (PMID 22235338, 2012). "Our previous work revealed that the low expression of CHD5 in colorectal cancer is correlated with CHD5 promoter CpG island hypermethylation." (PMID 22235338, 2012). "However, in another in vitro study that investigated the role of miR-211 in colorectal cancer, it was found that the enforced expression of miR-211 can promote cancer cell growth by suppressing the expression of CHD5, which is a tumor suppressor." (PMID 27663200, 2016). "Upregulation of miR-211 enhanced the proliferation of colorectal cancer cells may be by downregulating CHD5 and also promoted tumor growth in vivo." (PMID 22235338, 2012). "In addition, more studies are needed to validate the relationship between miR-211 and CHD5 in human colorectal cancer development and prognosis." (PMID 22235338, 2012). "Notably, several genes such as ALX4, CHD5, MYOD1, NEUROG1, and RASSF5, whose methylation profile distinguishes this group of HCC patients from the other HCC patients, were previously reported to be similarly hypermethylated and associated with poor prognosis in colorectal cancer." (PMID 25093504, 2014). "Colorectal cancer (CRC) is one of the three most prevalent cancers in the United States and CHD5 is frequently hypermethylated in human colon cancer cell lines and primary tumors." (PMID 22235338, 2012).
gastric cancer (6 papers, 2009 to 2024). A primary or metastatic malignant neoplasm involving the stomach. "Although promoter methylation frequently inactivates CHD5 in gastric cancer cell lines, we cannot exclude the presence of other mechanisms for the loss function of CHD5 in gastric cancer." (PMID 19840376, 2009). "The effect of ectopic CHD5 expression on the growth of gastric cancer cells AGS was determined with monolayer colony formation assay." (PMID 19840376, 2009). "In this study, we aim to study the involvement of CHD5 in gastric cancer, the second most common cancer worldwide." (PMID 19840376, 2009). "Methylation of CHD5 promoter was detected in all of seven gastric cancer cell lines and in the majority of primary gastric carcinoma tissues examined (73%, 11/15)." (PMID 19840376, 2009). "Instead, as shown in this study, CHD5 appears to be silenced predominately by promoter hypermethylation in gastric cancer." (PMID 19840376, 2009). "CHD5 expression was down-regulated in all of gastric cancer cell lines used (100%, 7/7) and significantly restored after pharmacological demethylation." (PMID 19840376, 2009). "The ectopic expression of CHD5 led to the growth inhibition of gastric cancer cells, indicating that CHD5 functions as a TSG epigenetically silenced in gastric cancer." (PMID 19840376, 2009). "Taken together, CHD5 was predominately silenced in gastric cancer and promoter hypermethylation appeared to be the major mechanism of CHD5 silencing in tumorigenesis of this tissue." (PMID 19840376, 2009). "The tumor suppression property of CHD5 in gastric cancer cells was investigated by a gain-of-function strategy." (PMID 19840376, 2009). "While CHD5 was highly expressed in normal gastric tissues, its expressions were down-regulated in all 7 gastric cancer cell lines (AGS, Kato III, MKN28, MKN45 and NCI-N87 SNU1 and SNU16)." (PMID 19840376, 2009). "The high incidence of CHD5 promoter hypermethylation in gastric cancer can be explored not only as a gastric cancer diagnosis but also prognosis prediction." (PMID 19840376, 2009). "The ectopic expression of CHD5 led to growth inhibition of gastric cancer cells, indicating that CHD5 functions as a tumor suppressor gene epigenetically silenced in gastric cancer." (PMID 19840376, 2009). "Here we found that, in contrast to other types of cancer reported so far, CHD5 was frequently hypermethylated in gastric cancer (73% of tumors and 100% cell lines)." (PMID 19840376, 2009). "The number of colonies formed on the plate by cells over-expressing CHD5 was significantly reduced (p < 0.01), indicating that CHD5 can suppress the growth of gastric cancer cells." (PMID 19840376, 2009). "CHD5 expression in these two cell lines were significantly increased after Aza-induced demethylation of CHD5 promoter, demonstrating that CHD5 is indeed epigenetically silenced in gastric cancer." (PMID 19840376, 2009). "In consistent with the data on gastric cell lines, the CHD5 promoter was also methylated in the majority of primary gastric carcinoma tissues tested (73%, 11/15)." (PMID 19840376, 2009). "The ectopic expression of CHD5 in gastric cancer cells led to a significant growth inhibition." (PMID 19840376, 2009). "The effect of CHD5 on growth of gastric cancer cells was tested by colony formation assay." (PMID 19840376, 2009). "However, the incidence of CHD5 promoter methylation in gastric cancer cell lines and tumors was found in this study to be relatively high, compared to the frequency of CHD5 methylation in other cancers (generally below 20%)." (PMID 19840376, 2009). "Moreover, methylation of CHD5 promoter in gastric cancer cell lines and gastric carcinoma tissues was confirmed by bisulfite genome sequencing (BGS)." (PMID 19840376, 2009). "CHD5 was a TSG epigenetically down-regulated in gastric cancer." (PMID 19840376, 2009).
gastric cancer (continued). "This striking correlation of the epigenetic suppression of CHD5 and gastric cancer suggests a previously unknown relationship between this TSG and gastric tumorigenesis." (PMID 19840376, 2009). "The expression of CHD5 in gastric cancer cell lines was determined by quantitative RT-PCR." (PMID 19840376, 2009). "CHD5 expression in a panel of gastric cancer cells were determined by quantitative RT-PCR." (PMID 19840376, 2009). "CHD5 was frequently down-regulated through promoter hypermethylation in gastric cancer cells." (PMID 19840376, 2009). "CHD5 expression is extremely low in MKN28 and SNU16, however, the promoter of CHD5 was only partially methylated in these two cell lines, indicating that other mechanisms may be responsible for the silencing of CHD5 in some of gastric cancer cell lines." (PMID 19840376, 2009). "Finally, ectopic expression of CHD5 in gastric cancer cells led to a significant growth inhibition." (PMID 19840376, 2009). "Recent studies have showed that CHD5 expression is silenced by epigenetical hypermethylation in the gene promoter in some tumors including HCC and gastric cancer." (PMID 29568352, 2018). "Whereas CHD5 is inactivated through copy number abnormality in various cancers, comparative genomic hybridization (CGH) indicated that 1p36, the CHD5-containing gene locus, is not significantly imbalanced in gastric cancers." (PMID 19840376, 2009).
Alzheimer disease (5 papers, 2011 to 2020). A progressive, neurodegenerative disease characterized by loss of function and death of nerve cells in several areas of the brain leading to loss of cognitive function such as memory and language. "In summary, we identified rs11121295 variant in CHD5 gene that was highly associated with risk of developing Alzheimer's disease from Chinese descent." (PMID 29861839, 2018). "Expression of gene sets linked to aging and Alzheimer's disease were strongly altered by CHD5 depletion from primary neurons." (PMID 21931736, 2011). "In addition, differential methylation of two genes associated with Alzheimer’s disease (CHD5 and DHCR24) was also observed in this study." (PMID 32033187, 2020). "Hypomethylation of CHD5 (−11.76%), which regulates genes implicated in aging and Alzheimer’s disease, and hypermethylation of DHCR24 (10.39%), which has neuroprotective characteristics and is downregulated in neurons of Alzheimer’s disease patients was observed in the reduced cognition group." (PMID 32033187, 2020). "Based on all of these findings, we set out to investigate whether CHD5 single-nucleotide polymorphisms (SNPs) were associated with risk of Alzheimer's disease in a two-stage case-control study from China." (PMID 29861839, 2018). "CHD5 is linked to regulation of genes implicated in aging and Alzheimer's disease." (PMID 21931736, 2011). "And then CHD5 directly regulated the targets including genes which are important for aging, Alzheimer's disease, and neuronal development." (PMID 29861839, 2018).
bladder cancer (3 papers, 2016 to 2022). "After discovery and confirmation, five genes MLL, EP400, PRDM2, ANK3 and CHD5 significantly correlated with the recurrence of bladder cancer." (PMID 26625313, 2016). "Meanwhile, through analyzing microarray data from GENT dataset, we found that CHD5 was underexpressed in 366 kidney cancer tissues, 87 bladder cancer tissues and 244 prostate cancer tissues, compared with the corresponding normal tissues." (PMID 26943038, 2016). "Additionally, the contribution of specific alterations of EP400, PRDM2, ANK3 and CHD5 to bladder carcinoma recurrence should also be further investigated." (PMID 26625313, 2016).
colon cancer (3 papers, 2012 to 2022). "In order to select the appropriate cell lines for our study, we evaluated the level of CHD5 protein in four colon cancer cell lines by Western blot analysis, which included two previously established cell lines (RKO and HCT-116) and two CHD5 transfected cell lines (RKO-S and RKO-AS)." (PMID 22235338, 2012).
developmental delay (3 papers, 2021 to 2023). "In conclusion, we describe the first cohort of patients with heterozygous variants in CHD5, associated with a new syndrome mainly characterized by developmental delay, intellectual disability, behavioral symptoms, and epilepsy." (PMID 33944996, 2021).
epilepsy (3 papers, 2021 to 2023). A brain disorder characterized by episodes of abnormally increased neuronal discharge resulting in transient episodes of sensory or motor neurological dysfunction, or psychic dysfunction. "Our findings suggest that, in line with other CHD-related disorders, heterozygous CHD5 variants are associated with a variable neurodevelopmental syndrome that includes intellectual disability with speech delay, epilepsy, and behavioral problems as main features." (PMID 33944996, 2021). "Taken together, these data suggest that several genes may be involved in the epilepsy phenotype of the 1p36 deletion syndrome and that CHD5 represents one of its potential modifiers." (PMID 33944996, 2021). "RERE haploinsufficiency might also play a role in the epilepsy of some patients with the 1p36 deletion, but this gene is located proximally to CHD5 and deleted only in patients with very large deletions [8/50 in]." (PMID 33944996, 2021). "Finally, 16/21 patients with a 1p36 deletion encompassing CHD5 were reported to display epilepsy, while 19/29 with retained CHD5 copy do not have epilepsy." (PMID 33944996, 2021).
Infertility (3 papers, 2016 to 2022). "It is worth noting that CHD5 was found highly expressed in the human testis during spermiogenesis and that low CHD5 expression was associated with some human infertile situations." (PMID 28031843, 2016). "For example, in a full body knockout of Chromodomain Helicase DNA Binding Protein 5 (CHD5), with phenotypes ranging from subfertility to infertility, the infertility is not caused by changes in the hypothalamic pituitary axis or somatic cell numbers." (PMID 35813619, 2022). "Instead, the infertility appears to be germ cell-intrinsic; presenting as defects in spermatid elongation and condensation defects, consistent with CHD5 expression in steps 7-10 of spermatid maturation, immediately preceding and overlapping with the extensive chromatin remodeling." (PMID 35813619, 2022).
Intellectual disability (3 papers, 2021 to 2023). "More recently, de novo and inherited missense mutations of CHD5 have been found in a small cohort of patients with intellectual disability, epilepsy and behavioural disorder of various severity." (PMID 37190088, 2023). "In addition to CHD3, CHD4 and CHD5, other highly related members of the CHD superfamily, CHD2, CHD7 and CHD8 have also been implicated in ASD and intellectual disability." (PMID 37190088, 2023). "Depending on the extent of the chromosomal deletion, CHD5 haploinsufficiency could contribute to the clinical features of this disorder or worsen the severity of intellectual disability, as previously suggested." (PMID 33944996, 2021). "Patients with CHD5 variants share nonspecific clinical features with the 1p36 deletion syndrome, a disorder characterized by moderate-to-severe intellectual disability, language deficits, hypotonia, seizures, and distinctive facial features." (PMID 33944996, 2021).
melanoma (3 papers, 2008 to 2022). A malignant, usually aggressive tumor composed of atypical, neoplastic melanocytes. "To evaluate if CHD5 is a major melanoma susceptibility gene in CMM/DN kindreds showing linkage to 1p36, we selected a panel of 16 individuals from eight CMM/DN families for sequencing of all CHD5 coding exons and their respective intron-exon boundaries." (PMID 18803848, 2008). "However, in patient tumors (of prostate and ovarian cancer, and melanoma), prevalence of somatic CHD5 mutations is low." (PMID 35768791, 2022). "Taken together, these results did not support CHD5 as a melanoma susceptibility gene in these eight families." (PMID 18803848, 2008). "In conclusion, we have not found evidence that CHD5 is a major melanoma susceptibility gene among the eight CMM/DN families screened." (PMID 18803848, 2008).
ovarian carcinoma (3 papers, 2012 to 2022). A malignant neoplasm originating from the surface ovarian epithelium. "Hypermethylation of CHD5 promoter has also been detected in gastric, colorectal and ovarian cancers, and somatic mutations have been detected in ovarian cancer." (PMID 22569290, 2012). "Mutation and promoter hypermethylation of the CHD5 gene was observed in ovarian cancer exhibiting reduced CHD5 expression." (PMID 24454811, 2014).
pancreatic cancer (3 papers, 2014 to 2019). "Low CHD5 expression and CHD5 depletion in several pancreatic cancer cell lines has been associated with DDR activation." (PMID 31769422, 2019). "CHD5 represses WEE1 transcription in PANC-1 pancreatic cancer cells, thus acting as a tumor suppressor." (PMID 31769422, 2019). "Similarly, low expression of CHD5 in pancreatic cancers correlates with lower survival following chemotherapy." (PMID 25247294, 2014). "Moreover, the CHD5 protein can be detected at the WEE1 promoter in pancreatic cancer cells that express endogenous CHD5." (PMID 25247294, 2014).
breast tumor (2 papers, 2009 to 2012). "Statistical analysis demonstrated that CHD5 mRNA expression was significantly reduced in breast tumors compared to their matched normal tissues (independent t-test, P < 0.05)." (PMID 22569290, 2012). "CHD5 protein expression was also significantly reduced in primary breast tumors, and lack of CHD5 expression correlated with higher tumor grade, local recurrence, distant metastasis and worse patient survival." (PMID 22569290, 2012).
gallbladder carcinoma (2 papers, 2015 to 2020). "CHD5 expression is associated with tumor grade and poor survival in primary gallbladder carcinoma patients." (PMID 26517514, 2015).
glioblastoma (2 papers, 2018 to 2022). The most malignant astrocytic tumor (WHO grade IV). "To investigate the biological function of CHD5 in glioblastoma progression, we subsequently performed loss-of-function experiments and silenced the expression of CHD5 in the human GBM cell line U87." (PMID 35955624, 2022). "However, myeloid-derived suppressor cells promote B cell-mediated immunosuppression through PD-L1 transfer in glioblastoma, which indicated that the tumor suppressor effect of CHD5 may not be through B cell immune function." (PMID 35955624, 2022).
head and neck squamous cell carcinoma (2 papers, 2021 to 2022). A squamous cell carcinoma that arises from any of the following anatomic sites: lip and oral cavity, nasal cavity, paranasal sinuses, pharynx, larynx, and salivary glands. "Evidence emerged that miR-24-3p targeted CHD5 to promote cells proliferation and regulate chemosensitivity in head and neck squamous cell carcinoma." (PMID 34305525, 2021).
lymph node metastasis (2 papers, 2012 to 2020). "Lower CHD5 mRNA levels correlated with lymph node metastasis (P = 0.026)." (PMID 22569290, 2012). "Results demonstrated that CHD5 was downregulated in tumor tissues and that low CHD5 expression was correlated with advanced TNM stage, high Fuhrman grade, lymph node metastasis, and poor survival." (PMID 33062682, 2020). "Our study showed that downregulation of CHD5 expression was related to advanced TNM stage, high Fuhrman grade, lymph node metastasis, and short overall survival." (PMID 33062682, 2020). "In brief, CHD5 is significantly downregulated in RCC tissues and cell lines, and downregulation of CHD5 was closely related to advanced TNM stage, high Fuhrman grade, and lymph node metastasis, as well as poor overall survival." (PMID 33062682, 2020).
1p36 deletion syndrome (1 paper, 2021). 1p36 deletion syndrome is a chromosomal anomaly characterized by distinctive facial dysmorphic features, hypotonia, developmental delay, intellectual disability, seizures, heart defects, hearing impairment and prenatal onset growth deficiency. "Notably, seizures are a frequent feature of patients with CHD5 point variants as well, hence supporting the epileptogenic role of CHD5 in the context of the 1p36 deletion syndrome." (PMID 33944996, 2021).
acute lymphoid leukemia (1 paper, 2017). "Human chromodomain helicase DNA binding protein 5 (CHD5), Krüppel-like factor 2 (KLF), Retinoblastoma protein-interacting zinc finger 1 (RIZ), and IKAROS family zinc finger 1 (IKZF1) are among the genes that regulates gene transcription, and are inactivated in acute lymphoid leukemia (ALL)." (PMID 28580304, 2017).
anaemia (1 paper, 2025). "While our study establishes proof of concept of the findings of our experimental animal research showing maternal iron deficiency anaemia as a significant factor for offspring CHD5, due to limited data, we were unable to assess whether iron deficiency is the cause of anaemia in the study population." (PMID 40264354, 2025).